ELOVL6 (ELOVL fatty acid elongase 6)
Description:
Catalyzes the first and rate-limiting reaction of the four reactions that constitute the long-chain fatty acids elongation cycle. This endoplasmic reticulum-bound enzymatic process allows the addition of 2 carbons to the chain of long- and very long-chain fatty acids (VLCFAs) per cycle. Condensing enzyme that elongates fatty acids with 12, 14 and 16 carbons with higher activity toward C16:0 acyl-CoAs. Catalyzes the synthesis of unsaturated C16 long chain fatty acids and, to a lesser extent, C18:0 and those with low desaturation degree. May participate in the production of saturated and monounsaturated VLCFAs of different chain lengths that are involved in multiple biological processes as precursors of membrane lipids and lipid mediators.
Synonyms: hELO2; FACE; LCE; FLJ23378; MGC5487; FAE
Tractability: Small molecule: a high-quality ligand is known; it belongs to a druggable protein family. Antibody: UniProt predicts a signal peptide or a membrane-spanning region. PROTAC: ubiquitination databases record sites on it; its protein half-life has been measured; a small molecule that binds it is known.
Target class: Enzyme; Transferase
Chemical probes: ELOVL6-IN-2 (high quality)
Gene: Protein-coding gene on chromosome 4 (110,045,846 to 110,199,199, reverse strand). Ensembl gene ENSG00000170522.
Subcellular location: Endoplasmic reticulum membrane
Pathways (Reactome):
Metabolism: Activation of gene expression by SREBF (SREBP); Synthesis of very long-chain fatty acyl-CoAs
Gene Ontology:
Molecular function: fatty acid elongase activity; protein binding; acyltransferase activity, transferring groups other than amino-acyl groups
Biological process: fatty acid elongation, saturated fatty acid; long-chain fatty acid biosynthetic process; fatty acid elongation, monounsaturated fatty acid; fatty acid elongation, polyunsaturated fatty acid; long-chain fatty-acyl-CoA biosynthetic process; positive regulation of cold-induced thermogenesis; sphingolipid biosynthetic process; fatty acid biosynthetic process; fatty acid elongation; unsaturated fatty acid biosynthetic process; very long-chain fatty acid biosynthetic process
Cellular component: endoplasmic reticulum; endoplasmic reticulum membrane; fatty acid elongase complex; membrane
Genetic constraint (gnomAD): Loss-of-function variants: 6 observed, 27.66 expected, observed/expected ratio (o/e) 0.22, 90% interval 0.12 to 0.43. The upper end of that interval is the gene's LOEUF score, 0.43, which puts it in group 1 of 6, group 1 being the genes least tolerant of losing a copy. Missense variants: 110 observed, 307.39 expected, observed/expected ratio (o/e) 0.36, 90% interval 0.31 to 0.42. Synonymous variants: 93 observed, 113.31 expected, observed/expected ratio (o/e) 0.82, 90% interval 0.69 to 0.98.
Homologues: Orthologues: chimpanzee ELOVL6 (100% identical), rabbit ELOVL6 (98% identical), macaque ELOVL6 (98% identical), guinea pig ELOVL6 (97% identical), mouse Elovl6 (97% identical), rat Elovl6 (97% identical), pig ELOVL6 (95% identical), tropical clawed frog elovl6 (90% identical), dog ELOVL6 (89% identical), zebrafish elovl6 (84% identical), Drosophila melanogaster Baldspot (47% identical), Caenorhabditis elegans elo-3 (42% identical), and 2 more. Paralogues in human: ELOVL3 (45% identical), ELOVL7 (28% identical), ELOVL1 (25% identical), ELOVL4 (25% identical), ELOVL2 (23% identical), ELOVL5 (23% identical).
Diseases named in the same sentence as ELOVL6 in open-access papers:
ELOVL6 is named in the same sentence as 79 diseases in open-access papers, as found by Europe PMC text mining. Sharing a sentence is not in itself a finding about the gene and the disease. The quoted sentences say what the papers report.
Insulin resistance (36 papers, 2011 to 2025). Increased resistance towards insulin, that is, diminished effectiveness of insulin in reducing blood glucose levels. "Noteworthy, the herein study has shown that treatment of obese and insulin-resistant rats with CBG caused a pronounced decrease in either ELOVL3 or ELOVL6 intramuscular expression." (PMID 38919749, 2024). "Insulin resistance involves upregulation of Elovl6, which has been linked to obesity-related malignancies, including hepatocellular carcinoma (HCC)." (PMID 29700319, 2018). "The function researches of ELOVL6 demonstrated that the deficiency of ELOVL6 in mouse protected against metabolic diseases such as insulin resistance, nonalcoholic steatohepatitis." (PMID 28414811, 2017). "Elovl6 has been shown to be associated with various pathophysiologies including insulin resistance, atherosclerosis, and non-alcoholic steatohepatitis." (PMID 27467521, 2016). "ELOVL6 is directly involved in the metabolism of C16∶1 and has been implicated in human obesity related insulin resistance." (PMID 23762394, 2013). "It has been proposed that inhibition of ELOVL6 activity could be a new therapeutic approach to combat insulin resistance, metabolic syndrome, and cardiovascular risk." (PMID 35807127, 2022). "Interestingly, mice deficient in Elovl6 (Elovl6−/−) are protected against diet‐induced insulin resistance despite their hepatosteatosis and obesity being comparable to that in wild‐type mice." (PMID 35748965, 2022). "Interestingly, liver deficiency of ELOVL6 significantly ameliorates insulin resistance in mice by modifying hepatic fatty acid composition." (PMID 22471940, 2012). "Impaired ELOVL6 activity has been demonstrated to affect metabolic balance between palmitate and stearate, thereby contributing to the development of insulin resistance and vascular dysfunction." (PMID 40564102, 2025). "Matsuzaka's research demonstrates that manipulating fatty acid components by blocking Elovl6 can prevent insulin resistance, impaired insulin secretion and obesity-related diseases." (PMID 37100872, 2023). "On the contrary, Elovl6, which catalyzes the transformation of palmitate to stearate, has been shown to contribute to insulin resistance." (PMID 37781111, 2023). "Mice with targeted disruption in the gene for Elovl6 (Elovl6 –/–) are resistant to diet-induced insulin resistance." (PMID 34977107, 2021). "Previous studies in mammals demonstrated that Elovl6 is also involved in inflammatory and metabolic diseases, such as high-fat-diet-induced inflammation and insulin resistance." (PMID 32050615, 2020). "The Elovl6−/− mice showed obesity and liver fat deposition, but at the same time they were protected against the high-fat and high-sucrose (HF-HS) diet induced insulin resistance." (PMID 32325903, 2020). "Metabolically, dwarfism protects from hepatic insulin resistance, reduces high-fat diet induced liver steatosis and suppresses de-novo lipogenesis genes including Elovl6, Acly and Fasn, thus indicating reduced lipogenic activity through Srebf1." (PMID 30462643, 2018). "Studies of ELOVL6 knockout mice have confirmed a crucial role for ELOVL6 in the development of insulin resistance, but its activity and relationship to plasma long‐chain FA has not been studied in human aging." (PMID 26522807, 2016). "We have previously shown that Elovl6 plays an important role in the development of hepatic insulin resistance and NASH by modifying FA composition." (PMID 26619823, 2015). "Data from mouse models discordant for obesity and insulin resistance (AKT2 KO, Adiponectin aP2-transgenic), suggested that scWAT TAG Elovl6 ratio was associated with insulin sensitivity, whereas SCD1 ratio was associated with fat mass." (PMID 26679101, 2015). "When Elovl6−/− mice were bred to ob/ob mice, an animal model of insulin resistance and obesity, the degree of obesity, fatty liver, hyperglycemia, or hyperinsulinemia were not different than in ob/ob mice." (PMID 25281760, 2014).
Insulin resistance (continued). "ELOVL6 and SCD1 genes are related to hepatosteatosis, obesity, and insulin resistance, all of which are associated with metabolic syndrome." (PMID 23476706, 2013). "In addition, the previous study indicated that inhibition of Elovl6, a key lipogenic enzyme elongating long-chain saturated and unsaturated fatty acids, can ameliorate insulin resistance in fatty livers and suppress fatty acid synthesis." (PMID 37114144, 2023). "Different studies indicate that the development of NAFLD is a result of insulin resistance, while liver fatty acids and the expression level of ELOVL6 (an enzyme that regulates fatty acid composition) are responsible for the development of insulin resistance and liver tissue fibrosis." (PMID 34445384, 2021). "In particular, we observe altered expression of genes previously reported to aggravate insulin resistance in both cell types, with the most profound changes seen for Cebpa (fold change 0.0096) and Lep (fold change 4.2) in 3T3-L1, ELOVL6 (fold change 8.88) and IL1B (fold change 3.92) in SGBS." (PMID 32718202, 2020). "Therefore, further studies of these DEP and DEPP would have profound significances for studying Elovl6 as a potential therapeutic target for many metabolic diseases such as type 2 diabetes, insulin resistance and fatty liver." (PMID 32325903, 2020). "Therefore, Elovl6 has been shown to increase insulin resistance in fatty livers, even with concurrent obesity in mice." (PMID 29700319, 2018). "ELOVL6 is believed to be involved in insulin resistance, lipogenesis, and obesity." (PMID 28589911, 2017). "An investigation of the relationship of these FA as predictors of insulin resistance in obesity and prediabetes may provide insight into the importance of ELOVL6 activity for insulin resistance in humans." (PMID 26522807, 2016). "As far as we are aware, no study has yet been done on ELOVL6 genetic variation in a human population and its possible association with insulin resistance or obesity-related disorders." (PMID 21701577, 2011). "In summary, we found that carriers of the minor alleles rs9997926 and rs6824447 of the ELOVL6 gene have lower insulin resistance than non-carriers and this effect is not independent of the type of oil consumed." (PMID 21701577, 2011). "Furthermore, Elovl6 also showed a crucial function for insulin resistance." (PMID 32050615, 2020). "Similarly, it was observed that mice deficient in ELOVL6 and fed a high fat diet developed obesity but not hyperinsulinemia, hyperglycemia, or insulin resistance." (PMID 33158152, 2020). "The activity of ELOVL6 is the best studied, in addition to its importance in adipogenesis as a target of the transcription factor SRBP1 and its effect in preventing insulin resistance when it is knocked down or knocked out in transgenic mice." (PMID 33158152, 2020). "In the cohort presented here, liver expression levels from statin-regulated lipogenic genes such as ELOVL6, SCD and FASN, which are under transcriptional control by SREBP1, were positively correlated with insulin resistance and the diabetic status." (PMID 31159817, 2019). "Interesting in this context are the recent observations that ELOVL6 promotes inflammation by C18-mediated lipotoxicity and immune interaction in NASH, diet-induced insulin resistance and atherosclerosis." (PMID 26862848, 2016). "The fatty acid-modifying enzymes for which connections to insulin resistance and T2D have been shown include delta-5, delta-6 and delta-9 desaturases (SCD-1) and elongase EloVL6." (PMID 26011768, 2015). "ELOVL6 promotes development of non-alcoholic steatohepatitis (NASH) and insulin resistance." (PMID 27902747, 2016). "Combined, the results suggest that the deletion of Elovl6 does not protect the mice from the development of insulin resistance induced by a high-fat diet." (PMID 25281760, 2014).
Insulin resistance (continued). "Combined, these results suggest that palmitoleic (C16:1, n-7) and vaccenic (C18:1, n-7) acids can largely replace the roles of oleic acid (C18:1, n-9) in vivo and that the deletion of ELOVL6 does not protect mice from the development of hepatic steatosis or insulin resistance." (PMID 25281760, 2014). "The dramatically lower transcript levels of ELOVL6 as well as PNPLA3 in hyperinsulinemic insulin-resistant subjects might have an impact to adipocyte lipid composition and could further decline adipose tissue function in insulin resistance." (PMID 22471940, 2012).
Obesity (32 papers, 2010 to 2025). Accumulation of substantial excess body fat. "Deactivating mutations in Elovl1 trigger hypomyelination, while deficiency of Elovl6 leads to general obesity in mice." (PMID 31766565, 2019). "In a similar manner, research on ELOVL6 identified that gene deletion in mice (Elovl6−/−) ensured resistance against diet-induced IR, although the mice were characterized by obesity and hepatic steatosis." (PMID 38919749, 2024). "The expression of elongases in the liver, particularly ELOVL5 and ELOVL6, is higher under the influence of a fatty diet and obesity, as shown by experiments on mice." (PMID 36291290, 2022). "This shows that in women, obesity and overweight are associated with a decreased expression of ELOVL5 and ELOVL6 in GBM tumors, whereas in men, the expression of these elongases is increased." (PMID 36291290, 2022). "Two inhibitors of ELOVL6 were able to reduce the fatty acid composition of hepatocytes and the liver in a murine model of obesity, but the effects of these compounds on cancer cells have not been explored." (PMID 31968678, 2020). "Elovl6 knockout mice are insulin resistant and develop obesity and hepatosteatosis when fed a high fat diet, indicating that ELOVL6 is important to normal metabolic regulation." (PMID 31616255, 2019). "Recently, inhibitors for mammalian ELOVL6 were developed, and the compounds were tested in diet-induced obesity animals and KKAy mice, a genetically obese and diabetic animal model." (PMID 25281760, 2014). "However, a few studies showing maintained insulin sensitivity despite diet-induced obesity and hepatosteatosis exist, e.g. FABP4 and 5 as well as Elovl6 deficient mice." (PMID 21738729, 2011). "Deficiency for Elovl6 protected high fat diet fed mice from hyperinsulinemia and hyperglycemia but not obesity and steatosis." (PMID 20346174, 2010). "To date, mutations in human ELOVL6 have not been linked with obesity or liver disease, however." (PMID 26935102, 2016). "Concomitantly, in red skeletal muscle induction of obesity by a diet rich in fatty acids significantly enhanced only ELOVL1 and ELOVL6 (+ 33.09%, + 35.54%, vs. the control group, respectively, p < 0.05)." (PMID 36879113, 2023). "ChREBP activation in WAT is altered in obesity, resulting in the downregulation of ChREBPβ, ACLY, ACACA, FASN, and ELOVL6." (PMID 32085416, 2020). "We discovered that the expression levels of ELOVL3, ELOVL5 and ELOVL6 increased similarly to estimated elongase activity (P<0.05), while the mRNA expression level of ELOVL1 decreased during the first year after obesity surgery (P=6 × 10−5)." (PMID 28869586, 2017). "In accordance with this concept, mice lacking Elovl6 exhibited obesity when housed at themoneutrality and fed a high-fat diet." (PMID 26628376, 2015). "When mice were fed a high-fat diet or ELOVL6 was deleted in ob/ob mice, the absence of ELOVL6 did not alter the development of obesity, fatty liver, hyperglycemia, or hyperinsulinemia." (PMID 25281760, 2014). "Moreover, induction of obesity by high-fat diet feeding markedly altered the expression of each examined isoform of ELOVL, namely ELOVL1, ELOVL3, and ELOVL6 (+ 65.04%, + 36.19%, − 37.34% and + 65.81%, vs. the control group, respectively, p < 0.05) in the white skeletal tissue." (PMID 36879113, 2023). "To further confirm that the lack of ELOVL6 did not influence the development of obesity and diabetes, we generated mice that lacked ELOVL6 and leptin (Elovl6−/−;ob/ob mice)." (PMID 25281760, 2014).
Hepatic steatosis (18 papers, 2010 to 2025). Steatosis is a term used to denote lipid accumulation within hepatocytes. "Mice fed the SF-Soy-HFD developed liver steatosis and showed increased transcript levels of genes associated with de novo lipogenesis (Acaca, Fasn, Scd1, Elovl6) and cholesterol synthesis (Hmgcr) pathways compared to those in the SF-Fish-HFD-group." (PMID 39165573, 2024). "Surprisingly, genes fundamental to lipid metabolism, including Scd1, Fasn, Elovl6, and Pnpla3-implicated in Fatty Liver Disease pathogenesis, were predominant in females." (PMID 23977068, 2013). "We further examined the expression of genes involved in de novo lipogenesis and TG synthesis in the liver after Gk knockdown in mice with HFD‐induced hepatic steatosis, including Acly, Acc1, Fasn, Elovl6, Scd1, Gpat, and Dgat." (PMID 39418169, 2024). "In mouse models, the knockout of key enzymes involved in lipid synthesis (e.g., Acc, Elovl6, Scd1, Gpat, or Dgat) reduces hepatic steatosis." (PMID 21079772, 2010). "Therefore it is likely that under the regulation of FOXA2 and Nrf2 diminished endogenous ALR levels in hepatic steatosis result in altered expression of lipid metabolizing genes such as ELOVL6, SCD1, CPT1α as well as FABP1." (PMID 28877220, 2017). "Increased expression of Elovl6 may contribute to the promotion of hepatic steatosis." (PMID 39600697, 2024). "At the same time, they concluded that deletion of ELOVL6 did not protect mice from developing hepatic steatosis." (PMID 40184169, 2025).
breast carcinoma (17 papers, 2010 to 2025). "HFD significantly down-regulated many of the genes found to be up-regulated in a lipid metabolic gene network associated with human breast cancer (e.g. Acyl, Insig1, Elovl6, Fasn, Scd)." (PMID 20435547, 2010). "ELOVL6 could be a therapeutic target for multiple cancers, and high ELOVL6 expression was associated with poor prognosis in patients with breast cancer." (PMID 36532007, 2022). "Additionally, Elovl6, a long fatty acid elongase involved in de novo adipogenesis, was found to be upregulated and associated to lymph node involvement and short relapse-free survival in breast cancer." (PMID 39333940, 2024). "Elongation of fatty acid is under the control of seven fatty acid elongases (Elovl) and expression of Elovl1 or Elovl6 is increased in breast cancer tissues." (PMID 36056008, 2022). "Notably, all the FA metabolic genes ELOVL6, ACSL1, ACSL3, ACSL4, ACDSB and ACAT1 showed significant positive correlation with NAT10 suggesting that overexpression of NAT10 in breast cancer patients is associated with FA metabolism." (PMID 36149760, 2022). "In addition, the excessive expression of ELOVL6 was found to be related to axillary lymph node metastasis and a short disease-free survival period in breast cancer, and a relationship was suggested to exist between excessive ELOVL6 expression and poor prognosis." (PMID 28851309, 2017). "Six of the 11 non-mitosis related genes were previously associated with poor survival in breast cancer patients: KRT17, MMP12, SLC7A5, SQLE, GABRP and PA2G4, but the remaining 5 had not been previously associated with cancer risk: CCDC86, NUP107, NUTF2, WASF1 and ELOVL6." (PMID 23077491, 2012). "Breast cancer cells are also characterized by elevated SCD1 and ELOVL6 activity, which contribute to a higher MUFA pool—especially OA—compared to non-cancerous cells." (PMID 41223946, 2025). "The rest of the genes above were also over-expressed metastatic cancers originating from breast cancer (ABCC5), kidney renal clear carcinoma (LRFN1), hepatocellular carcinoma (ELOVL6), and uveal melanoma (HTR2B)." (PMID 34680307, 2021). "Remarkably, ELOVL6 and SCD1 exhibited significantly higher expression levels in mutant RB tumors compared to those bearing wild-type RB in breast cancer and ovarian cancer patients." (PMID 28650445, 2017). "In aggressive prostate and breast cancer cells, FABP5 knockdown repressed the expression of genes involved in lipolysis, including HSL and MAGL, as well as that of genes involved in de novo FA synthesis, such as ELOVL6 and ACSL1." (PMID 33128030, 2020).